SPC24 (SPC24 component of NDC80 kinetochore complex)
Description:
Acts as a component of the essential kinetochore-associated NDC80 complex, which is required for chromosome segregation and spindle checkpoint activity. Required for kinetochore integrity and the organization of stable microtubule binding sites in the outer plate of the kinetochore. The NDC80 complex synergistically enhances the affinity of the SKA1 complex for microtubules and may allow the NDC80 complex to track depolymerizing microtubules.
Synonyms: SPBC24; FLJ90806
Tractability: Small molecule: a structure with a bound ligand is known. PROTAC: ubiquitination databases record sites on it.
Gene: Protein-coding gene on chromosome 19 (11,131,520 to 11,155,807, reverse strand). Ensembl gene ENSG00000161888.
Subcellular location: Nucleus; Chromosome, centromere, kinetochore
Subcellular location (Human Protein Atlas): Nucleoplasm; Nucleoli
Pathways (Reactome):
Cell Cycle: Amplification of signal from unattached kinetochores via a MAD2 inhibitory signal; EML4 and NUDC in mitotic spindle formation; Mitotic Prometaphase; Resolution of Sister Chromatid Cohesion; Separation of Sister Chromatids
Signal Transduction: RHO GTPases Activate Formins
Gene Ontology:
Molecular function: protein binding; microtubule binding
Biological process: attachment of spindle microtubules to kinetochore; chromosome segregation; mitotic spindle assembly checkpoint signaling
Cellular component: kinetochore; Ndc80 complex; nucleolus; nucleoplasm; nucleus; outer kinetochore; cytosol
Genetic constraint (gnomAD): Loss-of-function variants: 30 observed, 21.33 expected, observed/expected ratio (o/e) 1.41, 90% interval 1.05 to 1.84. The upper end of that interval is the gene's LOEUF score, 1.84, which puts it in group 6 of 6, group 1 being the genes least tolerant of losing a copy. Missense variants: 284 observed, 218.22 expected, observed/expected ratio (o/e) 1.3, 90% interval 1.18 to 1.44. Synonymous variants: 105 observed, 85.07 expected, observed/expected ratio (o/e) 1.23, 90% interval 1.05 to 1.45.
Homologues: Orthologues: macaque SPC24 (96% identical), pig SPC24 (88% identical), rat Spc24 (79% identical), chimpanzee SPC24 (78% identical), dog SPC24 (74% identical), mouse Spc24 (74% identical), tropical clawed frog spc24 (41% identical), zebrafish spc24 (34% identical).
Diseases named in the same sentence as SPC24 in open-access papers:
SPC24 is named in the same sentence as 28 diseases in open-access papers, as found by Europe PMC text mining. Sharing a sentence is not in itself a finding about the gene and the disease. The quoted sentences say what the papers report.
hepatocellular carcinoma (11 papers, 2015 to 2025). A malignant tumor that arises from hepatocytes. "LINC02154 also promotes proliferation and metastasis of hepatocellular carcinoma by activating the SPC24 and PI3K-AKT signaling pathways." (PMID 40529228, 2025). "Studies have shown that inhibiting the expression of SPC24 effectively suppressed cell proliferation and invasion in hepatocellular carcinoma." (PMID 38250721, 2024). "In some cancers, such as hepatocellular carcinoma and lung cancer, the OS time of patients with SPC24 high expression is significantly shorter than that of patients with low expression." (PMID 36718148, 2023). "SPC24 was also reported to be highly expressed in hepatocellular carcinoma and was an independent predictor of survival." (PMID 33553144, 2020). "High levels of CDCA1 (also known as NUF2, NDC80 kinetochore complex component), KNTC2 (kinetochore associated 2), SPC24, and SPC25 have been found to be correlated with colorectal and hepatocellular carcinoma tumors." (PMID 29029446, 2017). "SPC24 is an important component of the mitotic checkpoint machinery in the tumorigenesis and high levels of SPC24 have been found in colorectal and hepatocellular carcinomas, but its role in anaplastic thyroid cancer is still unclear." (PMID 28423533, 2017). "For instance, hsa-miR-7-5p was shown to target SPC24 expression in hepatocellular carcinoma cell lines, suppressing their proliferation and migration while also promoting apoptosis; however, the regulatory actions of hsa-miR-7-5p in A2780 OC cells remains to be defined." (PMID 39062744, 2024). "The NDC80 complex is composed of four components, comprising NDC80, NUF2, SPC24, and SPC25, and aberrant expression of these four components may cause uncontrolled cell proliferation in hepatocellular carcinoma." (PMID 38102624, 2023). "Genes, such as SPC24 and PKMYT1, are linked with the invasion of hepatocellular carcinoma cells, but these genes may be important for the invasion of BRCA cells." (PMID 31311202, 2019). "High SPC24 level has been reported for colorectal and hepatocellular carcinoma tumors." (PMID 29029446, 2017). "However, the functional role of SPC24 in hepatocellular carcinoma (HCC) remains unknown." (PMID 26515591, 2015). "Furthermore, high levels of SPC24, CDCA1 and SPC25 were correlated with colorectal and hepatocellular carcinoma tumors, suggesting the potential roles of this protein in cancer development." (PMID 28423533, 2017).
breast carcinoma (6 papers, 2017 to 2024). "Our study also found that SPC24 had the possibility of CNV mutation in Her2-positive breast cancer, and the expression increased as copy number increased." (PMID 32322168, 2020). "In breast cancer, SPC24 has been found to promote cancer development by regulating the PI3K/AKT pathway." (PMID 38250721, 2024). "The oncogenic role of SPC24 was also identified in breast cancer and lung cancer." (PMID 33553144, 2020). "Additionally, SPC24—which monitors the PI3K/AKT kinase pathway—is overexpressed in breast cancer, implying its importance in clinical treatment." (PMID 33013420, 2020). "Furthermore, in both MCF-7 and MDA-MB-231 breast cancer cell lines, it was confirmed that SPC24 knockdown leads to slower cell growth and increased apoptosis." (PMID 32322168, 2020). "Because SPC24 is a high-risk factor (i.e., the higher the expression, the greater the risk), this indicates that the CNV mutation of the gene will be indirectly involved in Her2-positive breast cancer progression by affecting its expression level." (PMID 32322168, 2020). "Interestingly, a few studies have shown that NDC80 is associated with PI3K/AKT, but the core component of its complex, SPC24, is defined to regulate the PI3K/AKT pathway in breast cancer cells and produce oncogenic effects." (PMID 37240068, 2023). "In conclusion, the overexpression of AURKB, GINS2, MCM10, UHRF1, POLE2, SPC24, and E2F2 in HER2-positive breast cancer patients with ALR showed that these hub genes could be potential prognostic biomarkers in such patients." (PMID 33013420, 2020).
lung carcinoma (6 papers, 2017 to 2023). "Consistent with this conclusion, we show that up-regulation of SPC24 is generally associated with poor prognosis of lung cancer patients." (PMID 29029446, 2017). "We also performed multiple Oncomine expression analyses for SPC24 in various lung cancer datasets with important clinical characteristics and risk factors, including staging, survival, recurrence, and smoking." (PMID 29029446, 2017). "We further performed multiple Oncomine expression analyses for SPC24 in various lung cancer datasets with important clinical characteristics and risk factors, including survival, recurrence, and smoking status." (PMID 29029446, 2017). "High expression of SPC24 can negatively regulate E-cadherin, and positively regulate N-cadherin and vimentin and participation in epithelial-mesenchymal transition during lung cancer, affecting tumor growth and invasion." (PMID 32226507, 2020). "Since smoking is the leading cause of small cell and non-small cell lung cancer, and contributes to more than 80 percent or more of lung cancer deaths, we further investigated the expression patterns of SPC24 among the lung cancer patients who were smokers." (PMID 29029446, 2017). "To reveal the role of SPC24, an important component of kinetochore, in the tumorigenesis of lung cancer, we performed Oncomine and immunohistochemistry (IHC) analyses for SPC24 in human lung adenocarcinoma tumors." (PMID 29029446, 2017). "From the clinical perspective, confirmation of SPC24 as a prognostic biomarker can benefit the diagnosis, management, and targeted therapy of lung cancer." (PMID 29029446, 2017). "SPC24 is a novel oncogene of lung cancer, and can serve as a promising prognostic biomarker to differentiate lung tumors that have various clinicopathological characteristics." (PMID 29029446, 2017). "In the current study, to the best of our knowledge, we for the first time provide evidence to support the oncogenic role of SPC24 in lung cancer development and progression." (PMID 29029446, 2017). "At time of sacrifice, the average weight of shSPC24 tumors were significantly smaller than the shN tumors (p < 0.05), suggesting SPC24 promotes tumorigenicity of lung cancer cells in vivo." (PMID 29029446, 2017). "In this study, we show direct evidence that down-regulation of SPC24, a key component linking inner and outer kinetochore, can reduce proliferation of lung cancer cells." (PMID 29029446, 2017). "Since SPC24 is up-regulated in lung adenocarcinoma, we wondered if SPC24 regulates cell growth and apoptosis in lung cancer." (PMID 29029446, 2017). "Concomitantly, the levels of Vimentin and N-cadherin were considerably down-regulated in siSPC24 cells, suggesting a promoting role of SPC24 in the regulation of epithelial-mesenchymal transition (EMT) for lung cancer." (PMID 29029446, 2017). "Taken together, knocking down SPC24 in NSCLC cells suppresses cell growth and promotes apoptosis, suggesting SPC24 positively regulates cellular proliferation and viability in lung cancer." (PMID 29029446, 2017). "Oncomine expression analysis show that SPC24 is over-expressed in lung adenocarcinoma tumors, providing another layer of evidence that SPC24 positively regulates lung cancer development." (PMID 29029446, 2017). "The fact that SPC24 is over-expressed in lung adenocarcinoma, especially in those of the advanced stages, is suggestive of a promoting role of SPC24 in tumorigenesis of human lung cancer." (PMID 29029446, 2017). "SPC24 and SPC25 are associated with genomic instability and disrupted regulation of cell cycle in lung cancer, but this gene might be responsible for progression of pituitary prolactinoma." (PMID 33709028, 2021). "Further Oncomine expression analyses on the lung cancer patients with short survivals recapitulated the over-expression pattern of SPC24 in the lung tumors: among the patients who died after one year, SPC24 levels were the highest compared with those who died three or five years later." (PMID 29029446, 2017).
lung carcinoma (continued). "Most importantly, SPC24 may serve as a promising prognostic biomarker for stratifying the lung cancer patients into clinically distinct groups that differ in staging, risk of smoking, recurrence, and survival." (PMID 29029446, 2017). "Our results confirm the oncogenic role of SPC24 in the development and progression of lung cancer." (PMID 29029446, 2017). "Considering SPC24 may promotes tumorigenesis of lung adenocarcinoma, this result suggests a possibility that SPC24 may mediate smoking-induced tumorigenesis in lung cancer (see Discussion)." (PMID 29029446, 2017). "Supporting the notion that SPC24 may positively regulate metastasis of lung cancer, SPC24-knockdown cells display markedly decreased migration and invasion." (PMID 29029446, 2017). "So far, both the in vitro and in vivo data suggest SPC24 promotes tumorigenesis of lung cancer." (PMID 29029446, 2017). "Thus, based on the results from the in vitro proliferation and invasion assays and the in vivo tumorigenicity assay, we conclude that SPC24 is a novel oncogene of lung cancer." (PMID 29029446, 2017). "Therefore, in the current study, we aimed at testing the hypothesis that SPC24 may promote tumorigenesis and progression of human lung cancer." (PMID 29029446, 2017). "In LUAD, previous study also found SPC24 is strongly expressed in LUAD and its level of expression is related to the survival rate for lung cancer patients." (PMID 32226507, 2020). "Transwell migration assay showed that knockdown of SPC24 significantly reduced migration of cells by 60% (A549, p < 0.05) to 80% (PC9, p < 0.01), suggesting a promoting role of SPC24 in lung cancer invasion." (PMID 29029446, 2017).
liver cancer (5 papers, 2015 to 2023). An epithelial or non-epithelial malignant neoplasm that arises from the liver. "We found that BIRC5, CDK1, NUF2, ZWINT, and SPC24 were highly expressed in liver cancer tissues, whereas expression was weak in normal tissues." (PMID 29190974, 2017). "LINC02154 increases liver cancer cell growth and spread by increasing SPC24 promoter activity and modulating the PI3K-AKT signaling pathway; it may also be used to estimate the prognosis of laryngeal squamous cell carcinoma." (PMID 37893009, 2023). "SPC24 has been considered as a biomarker for liver cancer and is upregulated in LIHC tumors." (PMID 34319007, 2021). "In addition, high expression of SPC24 is also found in thyroid cancer, liver cancer, and osteosarcoma 44-46." (PMID 32226507, 2020). "Our data shows that BIRC5, NUF2, and SPC24 may be promising liver cancer biomarkers that may not only predict disease occurrence but also potential personalized treatment options." (PMID 29190974, 2017). "Therefore, we suggested that BIRC5, NUF2, and SPC24 may be promising biomarkers in human liver cancer that provide information not only for predicting disease occurrence but also for suggesting personalized treatment options." (PMID 29190974, 2017). "High expression of SPC24 was significantly correlated with alpha-fetoprotein (AFP) (p = 0.044), median size (p = 0.030), tumor number (p = 0.019), and Barcelona-Clinic Liver Cancer (BCLC) stage (p = 0.015)." (PMID 26515591, 2015).
osteosarcoma (3 papers, 2017 to 2020). A usually aggressive malignant bone-forming mesenchymal neoplasm, predominantly affecting adolescents and young adults. "EGFR and p-ERK expression decreased significantly after Spc24 gene knockout, and osteosarcoma cell growth was significantly inhibited." (PMID 32322168, 2020). "By contrast, human osteosarcoma tissue samples showed high SPC24 and phospho-ERK levels and low E-cadherin levels." (PMID 29285250, 2017). "In this study, we investigated the role of the spindle checkpoint protein SPC24 in osteosarcoma progression." (PMID 29285250, 2017). "Next, we investigated the effects of SPC24 knockdown on in vivo osteosarcoma progression by xenografting control and SPC24 knockdown OS cells into dorsal flanking sites of 5 week old nude mice." (PMID 29285250, 2017). "This suggested that SPC24 mediated osteosarcoma metastasis by downregulating E-cadherin." (PMID 29285250, 2017). "Next, we investigated the role of SPC24 in osteosarcoma metastasis by Transwell invasion assays." (PMID 29285250, 2017). "SPC24 knockdown in 143B and U2OS osteosarcoma cells decreased cell growth, survival and invasiveness." (PMID 29285250, 2017).
anaplastic thyroid cancer (2 papers, 2017 to 2020). "All these results suggest that silencing SPC24 play a protective role in anaplastic thyroid cancer and can be targeted for the development of novel diagnostic and therapeutic strategies." (PMID 28423533, 2017). "In studying the role of SPC24 in anaplastic thyroid cancers, we demonstrated that silence of endogenous SPC24 by siRNA suppressed the proliferation of ATC." (PMID 28423533, 2017). "Our in vivo studies revealed SPC24 promoted tumor initiation and this was the direct proof for the function of SPC24 in anaplastic thyroid cancer progression." (PMID 28423533, 2017). "This is the first study demonstrating that SPC24 is involved in the regulation of E-cadherin expression in anaplastic thyroid carcinoma." (PMID 28423533, 2017). "SPC24 was previously identified to be highly expressed in anaplastic thyroid cancer." (PMID 33553144, 2020). "Moreover, knocking down SPC24 increased the expression of E-cadherin and inhibited cell migration and invasion of anaplastic thyroid cancer cells." (PMID 28423533, 2017).
bladder cancer (2 papers, 2012 to 2020). "Three SNPs in three genes (FBXO5, SMC3 and SPC24) were associated with significant protective effect on bladder cancer (Ptrend<0.05)." (PMID 22238607, 2012). "This regulatory role between SPC24 and hsa-miR-139-3p was previously observed in bladder cancer." (PMID 33553144, 2020).
thyroid cancer (2 papers, 2017 to 2020). "Quantified analysis for IHC of human thyroid cancer samples showed SPC24 was negatively associated with E-cadherin." (PMID 28423533, 2017). "The immunohistochemical analysis of human thyroid cancer samples indicated that the expression of SPC24 was high expressed compared to the normal samples." (PMID 28423533, 2017). "Statistical analysis endorsed that high levels of SPC24 was detected in human thyroid cancer samples." (PMID 28423533, 2017). "Our results showed that SPC24 was high expressed in human thyroid cancer samples." (PMID 28423533, 2017).
breast ductal carcinoma (1 paper, 2021). "In the Richardson dataset, the CCDC167 gene and its co-expressed genes, such as SAC3D1, SPC24, CENPM and DEPDC1B, were substantially upregulated in breast ductal carcinoma compared to the normal group." (PMID 33461170, 2021).
familial hypercholesterolemia (1 paper, 2022). An inheritable form of hyperlipidemia, in which there are excess lipids in the blood.
gastric cancer (1 paper, 2015). A primary or metastatic malignant neoplasm involving the stomach. "In Kaneko's report, mRNA of CDCA1, KNTC2, SPC24 and SPC25 was overexpressed in colorectal and gastric cancers compared with the corresponding normal mucosa, siRNA-mediated knockdown of either CDCA1 or KNTC2 significantly suppressed cell growth and induced HCC cell apoptosis." (PMID 26515591, 2015).
Hepatic hemangioma (1 paper, 2015). A congenital vascular malformation in the liver composed of masses of blood vessels that are atypical or irregular in arrangement and size. "SPC24 mRNA levels were aberrantly elevated in 18 of the 20 analyzed HCC tissues (90%) in comparison to non-tumor controls, while the SPC24 mRNA was faintly expressed in 9 cases of normal liver tissues from hepatic hemangioma' surrounding liver tissues." (PMID 26515591, 2015).
kidney cancer (1 paper, 2025). Primary or metastatic malignant neoplasm involving the kidney. "In addition, the relationship between miR-501-3p and SPC24 still needs to be uncovered in kidney cancer." (PMID 39907402, 2025).